LRP4 (LDL receptor related protein 4)
Diseases named in the same sentence as LRP4 in open-access papers (continued):
Sharing a sentence is not in itself a finding about the gene and the disease.
tumor (10 papers, 2015 to 2025). "In summary, our findings reveal that four of the identified characteristic genes (ADH1B, CCL27, ID4 and LRP4) are consistently downregulated in cSCC, and prior studies suggest their involvement in tumor proliferation, migration and invasion." (PMID 40296873, 2025). "Quantitative evaluation revealed consistent downregulation of ADH1B, CCL27, ID4 and LRP4 in tumor tissues compared to normal counterparts." (PMID 40296873, 2025). "We observed that globally LRP4 expression increased in the remaining tumor suggesting a broader role for LRP4 in treatment resistance also including chemo- resistance (adjusted p value=1.5e-06)." (PMID 40771583, 2025). "The antiproliferative effect of LRP4&AC on tumor cells consisted in cell-cycle arrest and induction of apoptosis." (PMID 37836464, 2023). "Having shown that LRP4 is essential for the emergence of iCSCs under radiation, we sought to investigate whether LRP4 expression is a more common biomarker of therapeutic response and could predict tumor recurrences." (PMID 40771583, 2025). "In addition, lactate dehydrogenase (LDH) increased in a concentration-gradient manner, confirming that LRP4&AC has a cytotoxic effect by inducing cell-membrane lysis in tumor cells." (PMID 37836464, 2023). "The results showed that the expression of IPCEF1, TFF3, GLT8D2, TPO and DIO1 were downregulated in the tumor group and DPP4, LRP4, CDH3, KCNJ2, CLDN1, GABRB2, FN1 were upregulated in the tumor group." (PMID 39513122, 2024). "While there is substantial evidence supporting the involvement of S100A9 in the tumor immune microenvironment and immune evasion, the roles of CCL27, ID4 and LRP4, genes that also showed strong correlations with infiltrating immune cells, remain inadequately explored." (PMID 40296873, 2025). "Importantly, overexpression of Lrp4 and MuSK in HCC tumours (8 out of 11 HCC patients) is consistent with the notion that Agrin functions through the Lrp4–MuSK complex to activate FAK in driving the oncogenic programme of HCC cells." (PMID 25630468, 2015).
neuromuscular disease (5 papers, 2014 to 2023). "Future experiments will reveal if NT-1654 can be of benefit in the treatment of human neuromuscular diseases that directly or indirectly affect the agrin/Lrp4/MuSK pathway." (PMID 24520420, 2014).
infection (3 papers, 2020 to 2025). The state of being infected such as from the introduction of a foreign agent such as serum, vaccine, antigenic substance or organism. "Locally reduction of Lrp4 expression level in hippocampus by sh Lrp4 lentivirus trans-infection increased the threshold of seizures of mice." (PMID 33292473, 2020). "The result showed that sh Lrp4 lentivirus trans-infection significantly decreased the relative Lrp4 protein level in mice hippocampus, compared to control (sh control lentivirus injection), but not sh Lrp4 scramble lentivirus trans-infection." (PMID 33292473, 2020). "Crucially, we could not adequately account for critical variables such as MG autoantibody subtype (AChR, MuSK, LRP4), patient age, and specific immunosuppressive regimens-all of which are known to influence infection risks and therapeutic responses." (PMID 41322303, 2025).
neurodegenerative disease (3 papers, 2021 to 2024). A disorder of the central nervous system characterized by gradual and progressive loss of neural tissue and neurologic function. "Once known in the nervous system only as the Agrin receptor at the NMJ, LRP4 has become a major player in various developmental processes and as an emerging neurodegenerative disease risk gene." (PMID 33799485, 2021).
neurological diseases (3 papers, 2014 to 2021). "The aim of this study was to test the presence and diagnostic significance of anti-LRP4 autoantibodies in an Italian population of 101 myasthenic patients (55 dSN, 23 AChR positive and 23 MuSK positive), 45 healthy blood donors and 40 patients with other neurological diseases as controls." (PMID 26284792, 2015). "Further experiments are needed to work out how LRP4 controls the learning process in the hippocampus and to explore the connection between LRP4 and various neuromuscular and neurological diseases." (PMID 25407677, 2014). "However, indeed, as the mechanisms for LRP4 function in the CNS are discovered, future studies will investigate its potential as a therapeutic target in a multitude of neurological disorders, seeking to connect synaptic function with disease progression." (PMID 33799485, 2021).
bone disorder (2 papers, 2016 to 2021). "Among the genes not previously identified through GWAS or not implicated as the index gene in an associated locus, LRP4 and COL11A1 are known to harbor rare mutations that cause monogenic skeletal disease in humans." (PMID 27612175, 2016).
cardiovascular diseases (1 paper, 2024). "Genetically predicted levels of LRP12, prothrombin, angiopoietin-1 (ANGPT1), and low-density lipoprotein receptor–related protein 4 (LRP4) were positively associated with VTE and 3 cardiovascular diseases." (PMID 38029854, 2024).
LRP4 also shares sentences with these, for which no sentence is quoted: Cenani-Lenz syndactyly syndrome (6 papers); atherosclerosis (2); cognitive deficits (2); Parkinson disease (2); Seizure (2); autism (1); congenital kidney malformations (1); cortical dysplasia (1); dementia (1); depression (1); fibrochondrogenesis (1); ghosal hematodiaphyseal dysplasia (1); glaucoma (1); heart disease (1); intellectual disability and (1); intervertebral disc degeneration (1); ischemic stroke (1); juvenile Paget disease (1); Lambert-Eaton myasthenic syndrome (1); lung carcinoma (1); melanoma (1); mental disorder (1); muscular dystrophies (1); myositis (1); Optic neuropathy (1); Paget disease (1); pancreatic cancer (1); renal hypoplasia (1); retinal ischemia (1); sterility (1).
A further 2 diseases each share a sentence with LRP4 in 1 paper.